TESPA1 (thymocyte expressed, positive selection associated 1)
Description:
Required for the development and maturation of T-cells, its function being essential for the late stages of thymocyte development (By similarity). Plays a role in T-cell antigen receptor (TCR)-mediated activation of the ERK and NFAT signaling pathways, possibly by serving as a scaffolding protein that promotes the assembly of the LAT signalosome in thymocytes. May play a role in the regulation of inositol 1,4,5-trisphosphate receptor-mediated Ca(2+) release and mitochondrial Ca(2+) uptake via the mitochondria-associated endoplasmic reticulum membrane (MAM) compartment.
Synonyms: KIAA0748; HSPC257; ITPRID3
Tractability: PROTAC: ubiquitination databases record sites on it.
Gene: Protein-coding gene on chromosome 12 (54,948,015 to 54,989,104, reverse strand). Ensembl gene ENSG00000135426.
Subcellular location: Cytoplasm; Endoplasmic reticulum membrane
Subcellular location (Human Protein Atlas): Cytosol
Gene Ontology:
Molecular function: phospholipase binding; signaling receptor binding
Biological process: COP9 signalosome assembly; positive regulation of T cell differentiation in thymus; positive regulation of T cell receptor signaling pathway; intracellular protein localization
Cellular component: COP9 signalosome; cytoplasm; cytosol; endoplasmic reticulum membrane; TCR signalosome
Genetic constraint (gnomAD): Loss-of-function variants: 33 observed, 57.81 expected, observed/expected ratio (o/e) 0.57, 90% interval 0.43 to 0.76. The upper end of that interval is the gene's LOEUF score, 0.76, which puts it in group 3 of 6, group 1 being the genes least tolerant of losing a copy. Missense variants: 618 observed, 642.47 expected, observed/expected ratio (o/e) 0.96, 90% interval 0.9 to 1.03. Synonymous variants: 227 observed, 236.25 expected, observed/expected ratio (o/e) 0.96, 90% interval 0.86 to 1.07.
Homologues: Orthologues: chimpanzee TESPA1 (99% identical), macaque TESPA1 (96% identical), pig TESPA1 (81% identical), dog TESPA1 (78% identical), guinea pig TESPA1 (76% identical), rabbit TESPA1 (71% identical), mouse Tespa1 (63% identical), zebrafish tespa1 (33% identical). Paralogues in human: ITPRID2 (25% identical), ITPRID1 (16% identical).
Diseases named in the same sentence as TESPA1 in open-access papers:
TESPA1 is named in the same sentence as 23 diseases in open-access papers, as found by Europe PMC text mining. Sharing a sentence is not in itself a finding about the gene and the disease. The quoted sentences say what the papers report.
acute myeloid leukemia (2 papers, 2023). Acute myeloid leukemia (AML) is a group of neoplasms arising from precursor cells committed to the myeloid cell-line differentiation. "On the other hand, Tespa1 is identified to be highly enriched in human acute myeloid leukemia (AML) cells and is essential for AML cell growth." (PMID 36997676, 2023).
asthma (2 papers, 2020 to 2025). "Although the average score of Tespa1−/− OVA mice was higher than that of WT OVA mice, it indicated that Tespa1 had little effect on the degree of inflammation during asthma attack." (PMID 33228696, 2020). "The analysis of Tespa1 mRNA expression in clinical samples including normal individual and asthmatic patients, showed that Tespa1 gene expression was lower, and IgE levels are higher in asthmatic patients, suggesting a relationship between Tespa1 and asthma." (PMID 33228696, 2020). "To detect the role of Tespa1 in the pathogenesis of asthma patients, we selected sputum from 33 patients with chronic asthma and 36 healthy individuals to test the expression of Tespa1 mRNA and IgE levels." (PMID 33228696, 2020). "Tespa1−/− mice were used for further in vivo experiments to extensively study the relationship between Tespa1 and the incidence of asthma." (PMID 33228696, 2020). "Results showed that compared with the healthy people, the level of Tespa1 mRNA expression of asthma patients was relatively lower, and IgE levels in the sputum of the patients were significantly increased (P < 0.05)." (PMID 33228696, 2020). "In this study, experiments have confirmed that Tespa1 negatively regulates mast cells during asthma, and this event is related to the IL-4/STAT6 signaling pathway." (PMID 33228696, 2020). "This study aimed to investigate the regulatory effect of Tespa1 on mast cells in the pathogenesis of asthma and its relationship with the interleukin (IL)-4/signal transducers and activators of transcription 6 (STAT6) signaling pathway." (PMID 33228696, 2020). "To further explore the role of Tespa1 in asthma, we assessed the OVA-induced asthma models of Tespa1−/− and WT mice." (PMID 33228696, 2020). "In this study, we observed that Tespa1 is associated negatively with the IL-4/STAT6 signaling pathway in the activation of mast cells, thus providing a new intervention target for mast cells in the pathogenesis of asthma." (PMID 33228696, 2020). "Tespa1-knockout mice (Tespa1−/−, KO) and C57BL/6 background (wild-type, WT) mice were sensitized and treated with ovalbumin (OVA) to establish an asthma model." (PMID 33228696, 2020). "Western blot analysis results of lung tissues showed that in Tespa1−/− asthma mice, the phosphorylation level of JAK1 increased, but the increase in P-JAK2 level was negligible, indicating that Tespa1 mainly regulates the IL-4/JAK1 signaling pathway." (PMID 33228696, 2020). "Thus, Tespa1 may be a potential target for asthma prevention and treatment." (PMID 33228696, 2020). "To study the effect of Tespa1 on STAT6 pathway, we detected the changes in IL-4 and IL-13 in the BAL of asthmatic mouse model, and the results showed that IL-4 and IL-13 in Tespa1−/− mice significantly increased compared with those in the WT asthma group." (PMID 33228696, 2020). "However, the role of Tespa1 in the IL-4/STAT6 signaling pathway, an important pathway for mast cell function and asthma pathogenesis, remains unclear." (PMID 33228696, 2020). "Altogether, our results indicate that Tespa1 can negatively regulate mast cell activity, and this event is related to the mast cell IL-4/STAT6 signaling pathway and could be therapeutically exploited to treat asthma attacks." (PMID 33228696, 2020).
rheumatoid arthritis (2 papers, 2018 to 2022). A chronic, systemic autoimmune disorder characterized by inflammation in the synovial membranes and articular surfaces. "Our previous studies found that Thymocyte-expressed positive selection-associated 1 (Tespa1) plays a critical role in the pathogenesis of human rheumatoid arthritis and mice collagen-induced arthritis, thus defining Tespa1 as a key gene in the pathogenesis of RA." (PMID 36110846, 2022).
allergic reactions (1 paper, 2020). "Tespa1 plays an important role in T cell development and negatively regulates Fc εR1-mediated mast cell activation and allergic reactions." (PMID 33228696, 2020). "Tespa1 is highly expressed in mast cells and is involved in the negative regulation of mast cell activation and mediation of allergic reactions by negatively regulating FcεRI-mediated signaling." (PMID 33228696, 2020).
Alzheimer disease (1 paper, 2022). A progressive, neurodegenerative disease characterized by loss of function and death of nerve cells in several areas of the brain leading to loss of cognitive function such as memory and language. "This hypothesis is intriguing as TESPA1 has also been identified as one of the top ten differentially expressed genes in a recent study investigating differential gene expression Alzheimer’s disease (AD) (compared to healthy controls) in several brain regions." (PMID 35705636, 2022).
autoimmune disease (1 paper, 2018). A disorder resulting from loss of function or tissue destruction of an organ or multiple organs, arising from humoral or cellular immune responses of the individual to their own tissue constituents. "To elucidate the possible role of Tespa1 in B cell-related autoimmune diseases, we induced CIA in bone marrow chimeric mice and showed that the development of CIA was clearly attenuated in Tespa1-deficient chimeras, suggesting that Tespa1 may be a potential therapeutic target in human RA." (PMID 29867947, 2018). "Taken together, our results suggest that Tespa1 may be a previously unsuspected missing component of the CD40-proximal signaling machinery in B cells, placing Tespa1 in a key position to regulate B cell-mediated autoimmune diseases and suggests possible new signaling pathways in B-lymphocytes." (PMID 29867947, 2018).
Cognitive impairment (1 paper, 2024). Abnormal cognition is characterized by deficits in thinking, reasoning, or remembering. "And the other two pairs of gene–gene interactions may be related to hippocampus, neuronal cells and cognitive impairment: TESPA1–OPCML and SCD5–SORBS1." (PMID 38368488, 2024).
leukemia (1 paper, 2023). A malignant (clonal) hematologic disorder, involving hematopoietic stem cells and characterized by the presence of primitive or atypical myeloid or lymphoid cells in the bone marrow and the blood. "Furthermore, data from cBioPortal and Vizome databases showed that no mutation of TESPA1 was present in patients with AML and no more than 0.1% mutations of TESPA1 in patients with other types of leukemia, suggesting that TESPA1 may be a relatively stable target for clinical treatment of AML." (PMID 36997676, 2023).
ovarian carcinoma (1 paper, 2023). A malignant neoplasm originating from the surface ovarian epithelium. "In the ovarian cancer TCGA RNA dataset, the expression levels of exons surrounding breakpoints of IGF2BP2 and TESPA1 did not change, and the overall expression of the genes did not correlate in any patient, suggesting that we detected an uncommon, patient-specific fusion." (PMID 38012143, 2023).
cancer (4 papers, 2023 to 2025). A tumor composed of atypical neoplastic, often pleomorphic cells that invade other tissues. "scDNA-seq also confirmed that the IGF2BP2::TESPA1 fusion was cancer cell-specific, as suggested by long-read scRNA-seq data." (PMID 38012143, 2023). "Short-read data however erroneously reported TESPA1 as the most differentially expressed gene in cancer cells, resulting from 3’ end capture of the fusion transcripts." (PMID 38012143, 2023). "Furthermore, we identify gene fusions, including an experimentally validated IGF2BP2::TESPA1 fusion, which is misclassified as high TESPA1 expression in matched short-read data, and call mutations confirmed by targeted NGS cancer gene panel results." (PMID 38012143, 2023). "TESPA1 was the highest differentially expressed gene in cancer cells compared to non-cancer cells in Patient 2 (Pcorr < 1.17 × 10−14)." (PMID 38012143, 2023). "In the HGSOC data set, the mtSNVs were called in most cancer and noncancer cells, and some fusion calls were expressed in most clones or subclones (P2: IGF2BP2::TESPA1, P1: SMG7::CH507-513H4.1, etc.), making them ideal variations for cell type reannotation and clustering." (PMID 40107722, 2025).
tumor (4 papers, 2021 to 2025). "The Patient-2 tumor sample yielded 453 total cells, with 208 (46%) identified as HGSOC cells, from which we identified 16 different malignant cell enriched fusion transcripts, including the earlier-identified IGF2BP2::TESPA1 fusion between chr3 and chr12 evident in 176/208 (85%) of the tumor cells." (PMID 38464114, 2024).
TESPA1 also shares sentences with these, for which no sentence is quoted: Alcohol use disorder (1 paper); atopic dermatitis (1); chronic asthma (1); cognitive decline (1); infection (1); liver cancer (1); liver diseases (1); malaria (1); pancreatic adenocarcinoma (1); pancreatic cancer (1); schizophrenia (1); Sepsis (1).